LAG3 (lymphocyte activating 3)
Diseases named in the same sentence as LAG3 in open-access papers (continued):
Sharing a sentence is not in itself a finding about the gene and the disease.
tumor (continued). "In addition, silencing of PRAME reduced the frequency of CD8+ T cells with expression of the immune checkpoints PD‐1, LAG‐3 and VISTA, indicating that PRAME tumour expression considerably impairs the PD‐L1/PD‐1 axis by dysregulating both the ligand and receptor." (PMID 34612587, 2021). "However, the intracellular signaling pathways of LAG3 and FGL1, both of which play a role in the regulation of immune cell function, cytokine production, and tumor growth, remain unknown." (PMID 35111155, 2021). "In addition, PD1, CTLA4, LAG3, TIM3 and GZMB were common inhibitory receptors (IRs) in the tumor microenvironment, which could inhibit immune responses and even cause immune escape or tolerance after binding with corresponding ligands." (PMID 34721537, 2021). "Interestingly, RBCK1 showed significant differential expression between cancer and normal tissues and was significantly related to tumor-infiltrating immune cells, including tumor purity and immune checkpoint molecules such as PD-L1, CTLA-4, LAG-3, and TIGIT in ccRCC." (PMID 34795663, 2021). "Finally, we also evaluated the additive effect of anti-PD-1 mAb or anti-PD-L1 mAb with/without anti-Tim-3 mAb with/without anti-Lag-3 mAb using tumor-specific CTL clones." (PMID 33611641, 2021). "In comparison to circulating immune cells, tumor infiltrating lymphocytes (TILs) have a greater expression of PD1, T-cell immunoglobulin and mucin containing protein-3 (TIM-3) or Lymphocyte-Activation Gene 3 (LAG3) in imatinib-naive as well as imatinib-sensitive and resistant-tumors." (PMID 34489967, 2021). "Nevertheless, this mutant LAG-3 could still inhibit T cells, demonstrating that FGL1/LAG-3 interactions correspond to a tumor immune evasion mechanism which is non-redundant to MHC-II binding." (PMID 34067904, 2021). "Furthermore, studies have shown that tumors with MMR defects can also contain other DNA repair defects, such as POLD or POLE mutations, and several immune checkpoint ligands, including PD-1, PD-L1, CTLA-4, LAG-3 and IDO, are also highly expressed in the tumor microenvironment of these patients." (PMID 33968789, 2021). "The fraction of cells carrying the exhaustion markers Lag-3, Tim-3, or PD-1 was comparable between Nr2f6+/+ and Nr2f6−/− CD8+OVAtet+ T cells, indicating that Nr2f6−/− cells do not become excessively exhausted 26, which is in contrasting our previous observations in tumor-infiltrating T cells." (PMID 33589606, 2021). "Notably, a strong cooperative effect between LAG-3, PD-1, and CTLA-4 has been elucidated in recent reports, highlighting the relevance of the interplay between these checkpoint molecules in the regulation of tumor immunity." (PMID 33430105, 2021). "Tumor cells mediate immunosuppression by hijacking inhibitory checkpoint proteins such as programmed death 1 (PD-1), T cell immunoglobulin and mucin domain 3 (TIM-3), lymphocyte activation gene 3 (LAG-3), and cytotoxic T lymphocyte antigen 4 (CTLA-4) expressed at the surface of T lymphocytes." (PMID 32316916, 2020). "Additionally, it is also suggested in 2017 that CD8+PD-1+Tim-3+Lag-3+ tumor-infiltrating lymphocytes, ICOS+ tumor-infiltrating Treg cells may be as significant factors for postoperative early relapse in localized RCC patients." (PMID 31956346, 2020). "Indeed, ex vivo experiments have shown that combined, rather than single blockade, of PD-1, Lag3 and Tim3, more efficiently rescues cytokine production and proliferative capacity of exhausted tumor-infiltrating CD4 and CD8 T-cells." (PMID 33207844, 2020). "The assay revealed novel insights and data at a single-cell resolution on the impact of PD1 and LAG3 inhibition (both separately and in combination) on CD8+ T cells activation by exposure to antigen-presenting cells such as dendritic cells and on CD8+ T cells tumor-killing function." (PMID 33188167, 2020).
tumor (continued). "Interestingly, the expression of DCK was associated with the gene markers like CCR8, STAT5b, and TGFB1 of Tregs, and PD–1, CTLA–4, LAG3, TIM–3, and GZMB of exhausted T cells after adjusting tumor purity, revealing that increased expression of DCK was associated with immunosuppression in HCC." (PMID 32690026, 2020). "This may suggest that elevated expression of PD-1, TIM-3, CTLA-4, TIGIT, TOX, TOX2, and SIRT1 genes in the TME of CRC is induced by tumor-associated, factors, unlike VISTA, and LAG-3." (PMID 32393998, 2020). "The OS in patients with LAG3 expression significantly improved compared to LAG3 negative tumours." (PMID 32592066, 2020). "Since virus-associated type I IFN upregulates inhibitory receptors on CAR T cells as well as PD-L1 and Galectin 9 on tumor cells, we reevaluated the therapeutic potential of CAR T cells with VSVGFP in combination with a cocktail of anti-PD1, anti-TIM3, and anti-LAG3." (PMID 32581235, 2020). "In our humanized mouse NPC-PDX model, the tumor-infiltrating CD8+ T cells expressed higher levels of PD-1 and CTLA-4, as well as LAG3, and these exhausted phenotypes might hinder the anti-tumor efficacy of ICB by suppressing their cytotoxicity and cytokine-producing capability." (PMID 32331230, 2020). "In addition, inhibitory receptors on the T-cell surface such as PD-1, LAG-3 and TIM-3 may bind to ligands that are expressed by tumour cells and actively impair T-cell responses." (PMID 32708397, 2020). "This suggests that activated CD8+ T cells in cluster L0, which express the immune inhibitory checkpoint molecules Tim3 (Havcr2) and Lag3, and which are enriched in transplant but not primary tumors, may mediate transplant tumor cure by anti-PD-1 therapy." (PMID 33335088, 2020). "However, comparing the expression pattern of the surface with the invasive tumour margin, a low heterogeneity was observed, only one case (0.6%) was positive for LAG3 on the surface and not on the invasive margin." (PMID 32592066, 2020). "Within a proinflammatory tumor microenvironment an activation-induced IFN-γ signature promotes the generation of MHC-II complexes and LAG3 recognition of stable peptide-MHC-II complexes is critical for activity, making LAG3 a surrogate biomarker of active inflammation in the tumor microenvironment." (PMID 32861198, 2020). "TIM-3 status on tumor cells did not appear to correlate with PD1+ TIL or LAG3+ TIL counts." (PMID 31007846, 2019). "Currently, the physiological roles in tumor surveillance by NK cells, as well as the therapeutic potential, of many surface receptors on NK cells have been demonstrated (e.g., KIR, TIGIT, NKG2A, CD96, and PD-1), while those of many others still remain to be shown (e.g., LAG-3 and TIM-3)." (PMID 31552017, 2019). "Since all OS tumours had CD8+ T-cell infiltration (of varying degrees) inferred from CD8A gene expression, we wanted to investigate the expression level of several T-cell inhibitory receptors PD-1, Tim-3, LAG-3, and CTLA4 using the RNA-seq data to assess the functional state of these CD8 + TILs." (PMID 30674975, 2019). "Second, many other factors such as IFN-γ+ Th1 response, CTLA-4, and LAG3-mediated effector T cell exhaustion are all involved in Treg-mediated tumor immune escape, which means that it is not possible to completely exclude the interference of other confounding factors on the results." (PMID 31930120, 2019). "Studies have shown that other immune checkpoints such as TIGIT, LAG-3, and TIM-3 may play a role in promoting tumor immune evasion and exhaustion of virus-specific T cells, suggesting that combination ICI therapy may need to be explored to effectively treat both cancer and chronic viral infection." (PMID 31847881, 2019). "Tumor-infiltrating cells with a TRM phenotype from advanced melanoma and lung cancer patients express higher inhibitory receptors such as PD-1, Tim3, and LAG3, which opens up the possibility that checkpoint blockade might promote the greater anti-tumor immunity by TRM cells." (PMID 31379821, 2019).
tumor (continued). "The success of these inhibitors in a number of tumour types has led to a search for novel checkpoints—T cell immunoreceptor with Ig and ITIM domains (TIGIT), T cell immunoglobulin and mucin domain-3 (TIM-3) and lymphocyte-activation gene 3 (LAG-3), which appear to be promising therapeutic targets." (PMID 31336704, 2019). "These exhausted CD8+ T cells express co-inhibitory molecules (e.g., PD-1, LAG-3, TIM-3, TIGIT) and lose the ability to produce multiple cytokines such as interferon (IFN)-γ, tumor necrosis factor (TNF)-α, and interleukin (IL)-2, namely they lose anti-tumor activities." (PMID 30696484, 2019). "Furthermore, tumor-specific increases in the percentages of Tim-3 and Lag-3 Tregs, CD8+ and non-Treg CD4+ T cells were observed, confirming that part of the tumor-infiltrating T cells has been activated." (PMID 31481117, 2019). "LAG3 is being targeted together with PD-1 in the dual immunomodulator MGD013 (ClinicalTrials.gov identifier: NCT03219268, phase I trial) whose objective is to inhibit both targets and induce a synergistic effect on tumor immunity, as previously shown in murine models." (PMID 31434339, 2019). "In addition, we observed that co-culture of DLBCL cell lines with primed T cells in the presence of anti-LAG-3 and anti-TIM-3 induced potent dose-dependent increases in in vitro cell death via AcellaTox and IL-2 ELISA assays, suggesting potent anti-tumor activity of these compounds." (PMID 31007846, 2019). "Secondly, there may be a significant discrepancy in LAG-3 expression between tumor locations that could not be detected by this study due to the small sample size." (PMID 31938638, 2019). "However, the tumor-infiltrated Tregs include heterogeneous subsets of cells expressing different immunosuppressive molecules favoring tumor progression, such as CTLA-4, PD-1, LAG-3, TIM-3, and TIGIT." (PMID 30718502, 2019). "This can be explained as the upregulation of LAG-3 in tumor tissue is not dependent on the DNA methylation but could be regulated by some other epigenetic modifications." (PMID 29983831, 2018). "However, CD8+ TILs separated from human HCC tissues are functionally exhausted as determined by upregulated expression of PD-1, Tim-3, CTLA-4, and lymphocyte activation gene 3 (LAG-3) compared with those from human CHB tissues, tumor-free liver tissues, and peripheral blood." (PMID 30309387, 2018). "In this study, NY-ESO-1 transduced T cells could infiltrate tumors and reduce tumor growth by 50%; however, the cells could not reduce tumor burden and showed upregulation of PD-1, Tim-3, and LAG-3." (PMID 29770138, 2018). "Besides, the LAG-3/MHC-II interaction may also act as bidirectional inhibitory signaling shared by immune cells and tumor cells." (PMID 30603054, 2018). "We could not find any obvious tumor-derived factors upstream of the upregulation of Ctla4 and Lag3 in the MLL-LNs." (PMID 28472073, 2017). "Interestingly, in our study, we also observed that the STAT3-blocked HCC vaccine could prevent tumor-induced exhaustion of CD8+ T and NK cells, as depicted by the downregulation of PD-1, TIGIT, and LAG-3 in HCC-vaccine-immunized mice." (PMID 29115974, 2017). "Interestingly, our recent work showed no expression of LAG-3 on tumor cells and immune cells in MPM tissue samples while our data in fluid samples showed its presence on T cells as well as NK cells." (PMID 29163783, 2017). "Thus, one role of LAG-3 blockade may be to increase proliferation of the antigen-specific CD8 TILs, while PD-1 blockade prevents T cell death or anergy through tumor cell PD-L1 ligation." (PMID 26910562, 2016). "In addition, upregulated expression of the immune checkpoints cytotoxic T lymphocyte-associated antigen 4 (CTLA4), programmed cell-death-1 (PD-1), programmed cell-death ligand-1 (PD-L1), lymphocyte activation gene 3 (LAG3) and indoleamine 2,3-dioxygenase (IDO) was noted in MSI tumours [34•]." (PMID 27340376, 2016).
tumor (continued). "The immune-checkpoint molecules lymphocyte-activation gene-3 (LAG-3), T cell ITIM domain (TIGIT), or T cell immunoglobulin and mucin domain-3 (TIM-3) may also contribute to the immune evasion of tumor cells because they are primarily expressed on exhausted T cells." (PMID 27847783, 2016). "Similar to LAG3 blockade, targeting TIM3 and/or BTLA may augment the efficacy of OX40 therapy by supporting the expansion, survival, and cytotoxic effector function of lymphocytes, particularly within the microenvironment of the tumor." (PMID 25763356, 2015). "LAG3 may enable the rapid translocation of PD1 from early/recycling endosomal compartments to the cell surface (near immunological synapse) via MTOC following T-cell activation and engagement with dendritic cells (or tumor cells)." (PMID 26318293, 2015). "Future studies using FRET (Fluorescence resonance energy transfer) technique in tumor infiltrating CD8+ T cells will help to determine whether and where these molecules directly interact and whether the colocalization of LAG3 and PD1 in TILs correlates with T cell dysfunction." (PMID 26318293, 2015). "Thus, while LAG3 and PD1 act synergistically to control immune homeostasis and mediate tumor-induced tolerance, the mechanism(s) of this synergy are currently unknown." (PMID 26318293, 2015). "In lymph nodes of the TCL1tg mice, a significant correlation between PDCD1 or LAG3 expression on T cells and tumour infiltration could be observed (Fig3), while there was no such correlation in the peripheral blood or spleen (not shown)." (PMID 25940792, 2015). "LAG-3 blockade alone does not always reverse the exhausted phenotype but can synergize with PD-1 blockade to improve effector functions and control viral load or induce tumor regression." (PMID 26347741, 2015). "Additionally, the presence of a highly immunosuppressive Tumor microenvironment (TME), enriched with regulatory T cells (Tregs), myeloid-derived suppressor cells (MDSCs), and the upregulation of alternative inhibitory receptors like LAG-3, TIM-3, and TIGIT, further impedes anti-tumor immunity." (PMID 41584608, 2025). "However, the expression levels of its receptor LAG-3 were significantly increased on tumor-infiltrating hepatic CD8+ T and NK cells from MC38 tumor–bearing mice compared with control mice, suggesting that there may be an FGL1/LAG-3 interaction in the liver tumor microenvironment." (PMID 38973608, 2024). "Furthermore, tumor-derived cholesterol can induce metabolic and ER stress in T cells preventing cytokine production by T cells and leading to increased immunosuppressive molecule expression (PD-1, TIM-3, or T cell immunoglobulin and mucin domain molecule 3, LAG-3, or lymphocyte activation gene-3)." (PMID 38339003, 2024). "Previous studies have shown low TMB levels, HLA loss, low CD8 infiltration, low LAG-3 or low TIM-3 expression to be associated with lower chance of response, but when addressing our intrapatient analyses of regressive versus progressive tumor lesions, these parameters did not validate." (PMID 38280045, 2024). "While targeting of CD200, TIGIT, and LAG3 is less established in GBM treatment, these targets should be highly considered for future drug development as they appear to be present in GBM and may serve as a strong alternative target should a patient’s tumor express low amounts of PD-1/PD-L1 or CTLA4." (PMID 39409893, 2024). "However, LAG-3 retention may render the ISG-15+CD8+ T cells into a terminal exhaustion state in non-responsive EBV (+) tumours." (PMID 37735150, 2023). "Notably, upon long-term in vitro ↑[H+] exposure, the frequency of TIM-3+LAG-3+ infiltrating OT-I T cells and CD19-CAR T cells within the tumors was largely reduced after adoptive transfer, which is consistent with their lower exhaustion in vitro and improved tumor control capacity in vivo." (PMID 36717749, 2023).
tumor (continued). "Indeed, CD8+ T cells in the tumor periphery showed increased expression of genes belonging to costimulatory pathways, including ICOS, TNFRSF4 (OX40) and TNFRSF9 (4-1BB), albeit accompanied by high levels of inhibitory receptors PDCD1 (PD-1), LAG3, HAVCR2 (TIM-3), and CTLA4." (PMID 38127790, 2023). "Furthermore, single cell RNA sequencing revealed a high heterogeneity of tumor infiltrating CD8+ T cells in CTCL skin with a strong variation in the expression of co-inhibitory receptors PD1, CTLA4, TIM3, LAG3, and TIGIT, which could affect capacity of tumor cell killing." (PMID 37691935, 2023). "Multiplexing assays utilizing highly sensitive and specific anti-LAG3 antibodies combined with additional biomarker specific antibodies, such as CD8, may prove useful for further assessing the relative biomarker distributions in various tumor types and thereby facilitate prognostic assessments." (PMID 36278613, 2022). "Moreover, the BsAb can not only target PD-1 and LAG-3 on single cell simultaneously, but also bridge the two kinds of cells expressing PD-1 and LAG-3, so as to release the ‘brake system of immune checkpoints’ and activate immune cells to exert anti-tumor effects more effectively." (PMID 36518768, 2022). "Therefore, cluster 2 of CM was considered the hot tumor to respond to immunotherapy because cluster 2 of CM displayed the characteristics of hot immune tumors, such as a high degree of CD8+ T cells, high immune score, more active immune functions, and higher expression of CTLA4, TIM3, and LAG3." (PMID 36199579, 2022). "Despite the fact that unknown results exist with regards to LAG-3 clinical studies, their rationale is founded on the data that suggest the co-targeting of LAG-3 as a promising strategy in order to improve the responses of immunotherapy in several human tumor types." (PMID 35145371, 2022). "In addition, increased LAG3 and CTLA4 expressions in the high-PYCARD group suggested the presence of a suppressive immune microenvironment and exhaustions of active immune cells, which may promote immune escape and tumor progression." (PMID 36291776, 2022). "Our present study first reported that the combination of LAG3 blockade and MWA could extend the survival and postponed tumor development in the MC38 bilateral tumor model, and the combination therapy could reprogram the TME to an anti-tumor manner via promoting the functions of CD8+TILs." (PMID 36180876, 2022). "In one human study, the presence of anti-LAG3 blocking mAbs or a recombinant soluble form of LAG3 did not influence LAG3+ NK cell cytotoxicity against multiple tumor cell lines, suggesting that in humans, LAG3 may not have a major influence on NK cell activity." (PMID 33572396, 2021). "There is evidence that T cells lose their effector function and ability to kill tumor cells when stimulated by tumor antigens, which may be due to the increasing diversity and number of inhibitory receptors, including CD274, PDCD1LG2, HAVCR2, CTLA4, LAG3, PDCD1, TIGIT." (PMID 33592580, 2021). "In the group of pT1/2 tumours, a LAG3 dependent survival difference could not be revealed." (PMID 32592066, 2020). "However, when looking at the expression level, we observed relatively high expression of LAG3 and HAVCR2 in both primary and recurrent tumor and a trend of greater expression for TIGIT, CTLA4, BTLA, and PDCD1 in recurrent tumor tissue, compared to primary tumor tissue (NS)." (PMID 33352957, 2020). "Furthermore, 70–80% of T cells in the tumor microenvironment of ML/CT-2A tumors exhibit prolonged expression of T cell immunoglobulin and mucin domain-containing protein 3 (TIM-3) and lymphocyte-activation gene 3 (LAG-3), both markers for dysfunctional T cells." (PMID 33374542, 2020).